MMP9 (matrix metallopeptidase 9)
Diseases named in the same sentence as MMP9 in open-access papers (continued):
Sharing a sentence is not in itself a finding about the gene and the disease.
lung carcinoma (continued). "The results showed that the overall survival rate was lower in patients with lung cancer and LUSC with high MMP9 expression (p = 0.046 and p = 0.01, respectively)." (PMID 37978381, 2023). "TMEM48 knockdown showed decreased MMP-2 and MMP-9 expression in A549 and H1299 cells, indicating the role of TMEM48 in the invasion of lung cancer." (PMID 37367036, 2023). "In lung carcinoma 95-D cells, EGCG suppressed their invasion, downregulated the expression of MMP9, and reduced the nuclear localization of NF-κB." (PMID 36677584, 2023). "The PI3K/AKT/mTOR pathway plays an important role in lung cancer cell migration and invasion, specifically in the regulation of MMP2 and MMP9." (PMID 37111758, 2023). "An acidic microenvironment induces MMP2, MMP3, MMP9 and MMP13 expression to promote breast or lung cancer progression." (PMID 35414794, 2022). "From the findings, we can infer that any suppressive effects of coriloxin on the invasive ability of lung cancer cells are exerted independently of MMP-2 and MMP-9 activities." (PMID 35409350, 2022). "Ouabain, a well-known cardiac glycoside, was reported to inhibit lung cancer cell migratory behavior by suppressing FAK activity and downregulating MMP-9 and MMP-2." (PMID 36362132, 2022). "MMP-9 was recruited to the GEM/rafts by reduced GM1 levels, contributing to increased invasion and high metastasis in mouse Lewis lung cancer cells." (PMID 35558506, 2022). "In this study, our results showed that rhein have obviously affect in treatment of proliferation and metastasis of chemosensitive and chemoresistant lung cancer cells, and play a role via the Stat3/Snail/MMP2/MMP9 pathway." (PMID 35178453, 2022). "TAMs-induced matrix metalloproteinase-9 (MMP-9) and VEGF also mediate metastasis in a TNBC mouse model and primary lung cancer tissues." (PMID 36577970, 2022). "The expression of SLIT3 is downregulated in lung tumor tissues and silencing of SLIT3 in lung cancer cells induces epithelial-mesenchymal transition by downregulating E-cadherin and enhancing MMP2 and MMP9 expression." (PMID 35053460, 2022). "It has also been demonstrated that the novel system using MMP9-responsive MSNs could be used to effectively control site-selective drug delivery in a combination of two drugs (bortezomib and cisplatin) to achieve the optimal synergistic effect on the therapeutic efficiency of lung cancer." (PMID 36568152, 2022). "MSCs have been found to increase the secretion of matrix metalloproteinase 9 (MMP9) by activating ABL kinase in lung cancer cells, thereby promote the metastasis of lung cancer cells." (PMID 35860555, 2022). "PVT1 also increased the expression of MMP‐2 and MMP‐9 to promote EMT, which ultimately made lung cancer cells radioresistant." (PMID 33931980, 2021). "In lung cancer, SP1 participates in the induction of matrix metalloproteinase-2 (MMP-2) and matrix metalloproteinase-9 (MMP-9) to accelerate cell invasion." (PMID 34257529, 2021). "MMP2, MMP9 and MMP13 have been found upregulated and enhance the migration capability of lung cancer cells." (PMID 34820358, 2021). "Nontumor exosomes derived from adipocytes increase the activity of MMP9 by delivering MMP3 to lung cancer cells, thereby promoting the invasion and migration of lung cancer cells." (PMID 34511114, 2021). "The other MMPs including MMP1, MMP9 and MMP14 were differentially changed in three lung cancer cells depending on specific cell types." (PMID 34253166, 2021). "The correlation of IL-6 and MMP-9, as well as other correlations in adenocarcinoma and SqCC and differences in the biomarker concentrations among groups, allowed us to observe subtype characteristics that might possibly be used to differentiate these two most common subtypes of lung cancer." (PMID 34439874, 2021).
lung carcinoma (continued). "Novel ginsenoside derivatives AD-1 (40 mg/kg) and 4-XL-PPD (50 and 100 μM) are also reported to inhibit protein levels of MMP-9 and/or MMP-2 in athymic nude mice with A549 lung cancer cells and MGC-803 human gastric cancer cells, respectively." (PMID 33671187, 2021). "In this study, we found that alectinib and lorlatinib significantly reduced the expression of VIM, FN1, MMP-9, and MMP-7 and that finally inhibited the metastasis of lung cancer cells." (PMID 33091333, 2021). "Cell viability or apoptosis upon treatment with either MMP2 or MMP9 siRNA along with Aβ immunodepletion, showed that MMP2 is the predominant regulator of the cytotoxic effects induced by Aβ in lung cancer cells." (PMID 33958632, 2021). "Our results demonstrate that Sal suppresses TGF-β1-induced EMT by downregulating MMP-2 and MMP-9 through the AMPK/SIRT pathway, thereby inhibiting lung cancer cell migration and invasion." (PMID 33437206, 2021). "Afatinib more effectively sensitizes lung cancer cells (Lewis lung carcinoma cells) to radiation and decreases metastasis by inhibiting phosphorylation of EGFR and HER2 and partly by decreasing matrix metalloproteinase 9 (MMP-9) production." (PMID 34094980, 2021). "Progesterone is declared as a repressor of MMPs; this hormone by reduction of MMP9 and dephosphorylation of focal adhesion kinase (FAK) in lung adenocarcinoma cells inhibits migration and invasion of lung cancer cells." (PMID 34912332, 2021). "Triptolide administration impairs the metastasis of lung cancer cells via EMT inhibition and reducing the expression levels of matrix metalloproteinase-9 (MMP9)." (PMID 33670518, 2021). "Thus, to determine whether nano-EGCG has any effects on MMP-2 and MMP-9 in lung cancer cells, we first collected conditioned media of H1299 and CL1-5 cells treated for 24 hours with various concentrations of EGCG or nano-EGCG and analyzed the media through gelatin zymography assay." (PMID 32198390, 2020). "A study focusing on lung cancer also reported that extracts of Antrodia cinnamomea decreased expression of MMP-2 and MMP-9 as well as their activities, which was ascribed to dysregulation of ERK, JNK, p38, and PI3K/Akt signaling pathways." (PMID 32401928, 2020). "Analysis of secreted MMP9 in the culture supernatant demonstrated a large increase of MMP9 protein in the culture supernatant (SN) from PC9 and HCC827 lung cancer cells grown in the presence of MSCs compared to cancer cells grown without MSCs." (PMID 33119681, 2020). "Unexpectedly, we found that ABL tyrosine kinases are activated in lung cancer cells primed by MSCs and that inactivation of ABL kinases impairs MSC-induced MMP9 secretion and gelatinase activity." (PMID 33119681, 2020). "Our study proved that ERα in lung cancer cells can promote the signal cross‐talk between lung cancer cells and macrophages via the ERα/CCL2/MMP9 and CXCL12/CXCR4 pathways." (PMID 32356397, 2020). "Treatment with GNF5 or ABL001 greatly reduced MMP9 secretion in co-cultures of MSCs with either PC9 or HCC827 lung cancer cells." (PMID 33119681, 2020). "In the same line, in our study, electric field stimulation (dcEF: 300 mV/mm, 2 h) caused significant changes in the MMP9 gene (which belongs to the MMP family) of lung cancer CL1-0 cells, indicating that MMP9 should be an electric field-sensitive gene." (PMID 32210363, 2020). "Disruption of MMP‐9 protein stability via honokiol was through HDAC6 activity inhibition, and following the suppression lung cancer cell migration and invasion." (PMID 32180962, 2020).
lung carcinoma (continued). "In lung cancer cells, AQP1 knockdown had inhibitory effects on cancer cell proliferation and migration along with the downregulation of MMP‐9 expression." (PMID 32253832, 2020). "Accordingly, the results suggested that the suppression of migration and invasion activities by honokiol was through inhibiting HDAC6‐mediated Hsp90/MMP‐9 interaction and followed by MMP‐9 degradation in lung cancer." (PMID 32180962, 2020). "Here we report that ABL kinases are activated in lung cancer cells co-cultured with MSCs, and that ABL kinase activity is required for MMP9 secretion and activation in a panel of lung adenocarcinoma cells." (PMID 33119681, 2020). "It was demonstrated that Rab-37 suppresses lung cancer metastasis by mediating TIMP1 (tissue inhibitor of metalloproteinase) exocytosis, which inactivates extracellular matrix metallopeptidase 9 (MMP9) and suppresses cell invasion signalling." (PMID 31370342, 2019). "In lung cancer, both non-small cell lung cancer NSCLC and SCLC tumor samples showed significantly higher MMP-9 expression compared to normal tissues as well as elevated MMP-9 in serum samples." (PMID 30669448, 2019). "In lung cancer, PGE2 promotes metastasis by increasing MMP9 mRNA expression and inhibiting E-cadherin mRNA expression." (PMID 31477121, 2019). "Recent findings have confirmed that in lung cancer cells, siRNA-TMEM98 significantly suppressed the invasion and migration of human A549 and H460 cells through down regulating MAT1, MMP-2, MMP-9 and RhoC." (PMID 29152140, 2017). "In contrast, knockdown of NMI promoted lung cancer cell colony formation and migration, which were correlated with the increased expression of phosphorylated PI3K/AKT, MMP2/MMP9, β-cadherin and COX-2/PGE2." (PMID 29025423, 2017). "Assessment of MMP9 by zymography assays showed that co-treatment with TNF and TGF-β cytokines markedly induced secretion of pro-MMP9 at 24 hours in breast and lung cancer cells." (PMID 28423685, 2017). "Overexpression of NMI induced apoptosis, suppressed lung cancer cell growth and migration, which were mediated by up-regulation of the cleaved caspase-3/9 and down-regulation of phosphorylated PI3K/AKT, MMP2/MMP9, β-cadherin, and COX-2/PGE2." (PMID 29025423, 2017). "Nickel chloride promotes the invasive potential of human lung cancer cells through elevated IL-8, TGF-β, MMP2 and MMP9 expression." (PMID 29127306, 2017). "Our results indicate that curcumin treatment induces miR-98 expression and suppresses lung cancer invasion and migration by decreasing the levels of MMP2 and MMP9." (PMID 28587210, 2017). "MiR-98 overexpression suppressed lung cancer cell migration and invasion by inhibiting LIN28A-induced MMP2 and MMP9 expression." (PMID 28587210, 2017). "We analyzed the effect of reduced Nrf2 on A549 and H460 cells, two of the most aggressive lung cancer lines, for MMP-2 and MMP-9 expression." (PMID 28402268, 2017). "Daurinol treatment resulted in suppression of MMP2 and MMP9 as well as down-regulation of FAK phosphorylation in both breast and lung cancer cells." (PMID 28915654, 2017). "PEG10 has been reported to promote lung cancer cell migration and invasion by upregulating the expression of β-catenin, MMP-2 and MMP-9, and decreasing the expression of E-cadherin." (PMID 28193232, 2017). "Specifically, activated Rac1 regulates tumor invasion of lung cancer cells by regulating gene transcription of MMP2 and MMP9." (PMID 27164951, 2016). "Levels of VEGF, IL-8, matrix metallo-protease-9 (MMP-9) and MMP-2 were measured in serum samples of COPD and lung cancer patients, which were compared with HD." (PMID 27811960, 2016). "Our data demonstrate that S100A4 drives the invasive capacity of lung cancer cells, affects the NF-κB pathway, and acts as an essential component of TNF-α-induced and NF-κB-dependent MMP9 expression." (PMID 27127879, 2016).
lung carcinoma (continued). "The authors have demonstrated that curcumin reduces lung cancer cell metastasis through inhibition of MMP-2 and MMP-9 expression mainly by downregulation of Rac1/PAK1." (PMID 27834913, 2016). "Trans-FA treatment inhibited the migration and invasion of lung cancer cells and concurrently attenuated the activities of both MMP-2 and MMP-9." (PMID 27733866, 2016). "Collectively, these results indicate that celecoxib and sulindac antagonize the activation of MMP-9 and the phosphorylation of Smad2/3 promoted during TGF-β1-induced EMT in lung cancer." (PMID 27528025, 2016). "Compared to COPD patients, insignificant change in the levels of MMP-9 and MMP-2 were observed in the serum samples of lung cancer patients." (PMID 27811960, 2016). "Compared to HD, the level of serum MMP-9 was significantly (P < 0.05) increased in case of COPD and lung cancer patients." (PMID 27811960, 2016). "In these patients, except for MMP-2, the levels of other biomarkers (VEGF, IL-8 and MMP-9) followed a close proximity to COPD and lung cancer patients, but clearly differed from HD." (PMID 27811960, 2016). "Experiments performed by Wysoczynski and Ratajczak showed that EVs secreted by lung cancer support angiogenesis by promoting changes in stromal cells, increasing the expression of several pro-angiogenic factors (as IL-8, VEGF, OSM, MMP9)." (PMID 25797265, 2015). "Downregulation of ILK expression and CDDP treatment, in combination, is a more effective approach for the treatment of lung cancer through affecting downstream gene expression, including p-GSK3β, p-AKT, AP-1, β-catenin, cyclin D1 and MMP-9." (PMID 25760437, 2015). "Specifically, activated RhoA regulates tumor invasion of lung cancer cells by regulating gene transcription of MMP2 and MMP9." (PMID 25889562, 2015). "In lung cancer, uPA, its receptor (uPAR), and the inhibitors PAI-1 and PAI-2 of the plasminogen activator family interact with MMP-2 and MMP-9 of the MMP family to promote cancer progression." (PMID 26230665, 2015). "Initially, we focused on MMP2 and MMP9, because high expression of MMP2 or 9 is commonly observed in various cancers including lung cancer, and their expression is positively correlated with tumor malignancy and poor diagnosis of cancer patients." (PMID 24318272, 2013). "Overexpression of MMPs is correlated with the progression of lung cancer, and the expression of either MMP-2 or MMP-9 confers a worse prognosis in early-stage lung adenocarcinoma." (PMID 24023938, 2013). "Meanwhile the distinct role of Kindlin-1 and Kindlin-2 in the regulation of lung cancer cell invasion was examined by determination of the expression of metalloprotenases including MMP7, MMP9 and MMP13." (PMID 23209705, 2012). "In conclusion, our results indicate that overexpression of VEGF enhances the growth of Lewis lung cancer cells, stimulates the production of COX-2, MMP2, MMP9 and enhances the functional activities of MMP2 and MMP9 in vitro." (PMID 23226772, 2012). "Expression of MMP-9 has been reported in breast, colon, and lung cancers, as well as skin tumors, and the expression of both MMP-2 and MMP-9 has been correlated with local invasion of the tumor, lymph node metastasis, and survival rates." (PMID 22159401, 2012). "Using western blotting, we found that A549 cells treated with PD98059 showed decreased expression of both MMP9 and calpain-2, suggesting that ERK1/2 regulates the expression of these proteins in A549 lung cancer cells." (PMID 19568240, 2009). "Taken together, our findings support the view that fibronectin induces the activation of FAK which then activates both the ERK1/2/MMP9 and ERK1/2/calpain-2 pathways to promote lung cancer cell invasion and migration, respectively." (PMID 19568240, 2009).
lung carcinoma (continued). "Specifically, CUR inhibits STAT3 phosphorylation and activation in lung cancer cells, leading to a 40%–60% reduction in tumor size and a significant decrease in the expression of STAT3 target genes such as cyclin D1, VEGF, MMP2, and MMP9." (PMID 40860906, 2025). "This study indicates that esketamine does not affect the perioperative changes in MMP‐9 levels in lung cancer patients." (PMID 40808216, 2025). "Similarly, gold nanorods delivering miR-320a increased apoptosis and suppressed cell proliferation and metastasis in lung cancer models by enhancing PTEN (phosphatase and tensin homolog) expression and inhibiting MMP-9 (matrix metallopeptidase 9) activity." (PMID 40260417, 2025). "Compared with normal lung tissues, the expression of MMP3, MMP9, and PPARG was increased in lung cancer tissues, and the expression of ALOX5 and ICAM1 was decreased in lung cancer tissues, which was basically consistent with the analysis results in the GEPIA database." (PMID 39440769, 2025). "FA could induce cell death of cell lung cancer cells (H1299) at a concentration of 0.06–0.6 μM by upregulating ROS, hydrogen peroxide, superoxide anion, and downregulating MMP2 and MMP9, colony formation, and AIG capacity." (PMID 40487371, 2025). "Moreover, TNCL binds more effectively to the MMP-9 3′-UTR zone than the full NCL, reducing MMP-9 transcript degradation in H1299 and A549 lung cancer cell lines." (PMID 38069210, 2023). "Our results showed that rhein plays a vital role in proliferation and metastasis of chemosensitive and chemoresistant lung cancer cells, and the mechanism may be related to the Stat3/Snail/MMP2/MMP9 pathway." (PMID 35178453, 2022). "Strikingly, MICE and HIIE markedly reduced the expression of MMP9 and MMP2 in lung cancer tissues, respectively, which means that MICE may restrain the metastasis of lung cancer cells by decreasing the level of MMP9." (PMID 35371324, 2022). "In addition, overexpression of SCARA3 reduced migration and invasion ability of lung cancer cells and induced decreases of EMT markers such as β-catenin, vimentin, and MMP9." (PMID 35578316, 2022). "We found that although the expression of MMP2 in lung cancer tissues did not increase, the expression level of MMP9 tended to increase (P=0.08)." (PMID 35371324, 2022). "Furthermore, we analyzed the correlation of the expression of hub gene in lung cancer tissues, of which PECAM1, VWF, CD34, COL1A1, MMP9 and TIMP1 are closely related." (PMID 33850663, 2021). "Among these, the p38 inhibitor showed potent inhibitory effects on MMP-9 production, suggesting that p38 kinases may be more critical than ERK and JNK kinase in TGF-β-mediated MMP-9 induction in lung cancer cells." (PMID 34769032, 2021). "Interestingly, the estrogen receptor α promotes cancer cell invasion via the increase of and cross-talk with infiltrated macrophages through the CCL2/CCR2/MMP9 and CXCL12/CXCR4 signaling pathways at least in lung cancer." (PMID 34833360, 2021). "In the present study, we showed that MMP-2 and MMP-9 activity mediates Sal's anti-invasive and anti-migratory effects by downregulation through the AMPK/SIRT pathway, thereby inhibiting the invasion and metastasis of lung cancer cells." (PMID 33437206, 2021).